RNU6-500P (RNA, U6 small nuclear 500, pseudogene)
Gene: Small nuclear RNA gene on chromosome 5 (173,362,134 to 173,362,240, reverse strand). Ensembl gene ENSG00000199219.
Homologues: Orthologues: chimpanzee U6 (97% identical), macaque U6 (93% identical), guinea pig U6 (85% identical), rat LOC120096742 (83% identical). Paralogues in human: RNU6-1287P (88% identical), RNU6-1209P (86% identical), RNU6-1331P (86% identical), RNU6-797P (86% identical), RNU6-1091P (85% identical), RNU6-115P (85% identical), RNU6-727P (85% identical), RNU6-1011P (84% identical), RNU6-1131P (84% identical), RNU6-1330P (84% identical), RNU6-1340P (84% identical), RNU6-23P (84% identical), and 1287 more.